PARP1 (poly(ADP-ribose) polymerase 1)
Diseases named in the same sentence as PARP1 in open-access papers (continued):
Sharing a sentence is not in itself a finding about the gene and the disease.
diabetes (continued). "Apart from being resistant to septic shock, PARP1 null mice show a certain degree of protection from other disease induction, such as ischemic stroke, traumatic brain injury, and streptozotocin-induced diabetes, indicating the role of PARP1 in the pathogenesis of these diseases." (PMID 31842403, 2019). "Also, PARP-1 knockout mice have been shown to be protected from induced diabetes." (PMID 29392078, 2018). "Although previously implicated in the mediation of diabetes microvascular complications, PARP-1 has not been an obvious candidate in the direct pathogenesis of T2D, with a known role principally in DNA damage repair through repair of single-strand and double-strand breaks." (PMID 29392078, 2018). "Besides Cxcl12, PARP-1 is also involved in the regulation of several other diabetes-related genes." (PMID 23555743, 2013). "Similarly, the protein expressions of PARP-1/2 were upregulated by diabetes in the retina." (PMID 24347828, 2013). "The outcomes demonstrated that diabetes elevated miR-34a, p66Shc, CASP3, and PARP1 and downregulated let-7a-5p and SIRT1 expression." (PMID 38129872, 2023). "PARP1 knockout can inhibit the signal transducer and activator of transcription 1 (STAT1)/RUNX2 axis and reduce AIC in diabetes." (PMID 37679327, 2023). "It was observed that the activation of PARP-1 and the decrease of the levels of NAD+ and SIRT1 in diabetes were dose-dependent with oral administration of polyphenolic cocoa extract." (PMID 32013273, 2020). "They observed that in diabetes mellitus, SIRT1 activity was reduced by PARP-1 activation and NAD+ depletion due to low concentration of AMPK increasing NOX4 expression." (PMID 32013273, 2020). "Recently, PARP1 and XRCC6 have been proved crucial for fundamental cellular processes, metabolism, ageing, and related diseases, such as cancers, diabetes, neurodegenerative, and cardiovascular diseases." (PMID 29367615, 2018). "A significant increase in both the mRNA and protein expressions of PARP-1 as well as its localization in the glomerulus was evident from our study strongly supports and reaffirm the involvement of PARP-1 in diabetes." (PMID 28883608, 2017). "Consequently, PARP-1 inhibitors, such as nicotinamide and 3-aminobenzamide, have been used to treat STZ-induced diabetic rat models, leading to a significant reduction in angiostatin isoforms, a key regulator of angiogenesis." (PMID 40072104, 2025). "Moreover, polyphenol-enriched cocoa treatment decreased PARP-1 activity and improved sirtuin-1 (SIRT-1) activity in animal models for hypertension and diabetes (SHR-STZ rats)." (PMID 39458649, 2024). "For example, PARP-1 knockout mice did not develop diabetes when induced by the beta-cell toxin streptozotocin." (PMID 39458649, 2024). "To ensure that we would be able to detect a protective effect against STZ-induced beta cell death in our experimental setup, we tested the Poly (ADP-Ribose) Polymerase 1 (PARP1) inhibitor Olaparib, since PARP1 KO mice are strongly protected against STZ-induced diabetes." (PMID 36470401, 2023). "PARP1 knockout can inhibit the STAT1/RUNX2 axis and reduce AIC in diabetes." (PMID 37679327, 2023). "The role of PARPs in diabetes has been explored for the last thirty years, with early studies employing PARP-inhibitors in isolated β cell function, while later reports investigated the action using PARP1−/− mice or derived cells." (PMID 36513699, 2022). "In addition, PARP1, poly(ADP-ribose) polymerase 1, is related to immune response, inflammation, and infection responses in diabetes." (PMID 35941691, 2022). "Aside from its potential to stimulate β-cell regeneration and prevent apoptosis, capability of CXCL12 to prevent pancreatic β-cells from entering the necrotic cell death by modulating PARP-1 activity, places chemokine CXCL12 in the focal point of developing strategies for diabetes treatment." (PMID 24988468, 2014).
diabetes (continued). "However, the potential link between PARP-1 regulation and diabetes-induced atherosclerotic calcification has not been examined." (PMID 31924749, 2020). "After 12 weeks of diabetes, diabetic mice showed higher levels of blood glucose, total plasma cholesterol, and triglyceride, whereas PARP-1 deletion had no obvious effect on mice body weight, blood glucose, total cholesterol, triglyceride, serum calcium, or phosphorus levels." (PMID 31924749, 2020). "Diabetes is characterized by high glucose levels in the circulation which increases endothelial ROS production through auto-oxidation of glucose, NADPH-oxidases, eNOS uncoupling, and mitochondrial dysfunction, leading to DNA damage and subsequent activation of poly(ADP-ribose) polymerase 1 (PARP1)." (PMID 30131957, 2018). "In addition, alteration of MMPs-9, −13 and −14 expression, PARP-1, HIF1α, and increased collagen biosynthesis as well as collagen cross-linking protein, P4HA1 and PLOD2 were observed along with diminished vascular density in diabetic kidney." (PMID 28883608, 2017). "The involvement of PARP-1 in β-cell death is confirmed by the observation that pharmacological inhibition or genetic deletion of PARP-1 protects animals against the development of chemically-induced diabetes and protects NOD mice from spontaneous diabetes development." (PMID 24988468, 2014). "Diabetic mice lacking iNOS or PARP1 (poly(ADP-ribosyl) polymerase) in their bone marrow-derived cells, likewise were protected against development of the diabetes-induced oxidative stress, induction of inflammatory proteins, and degeneration of retinal capillaries." (PMID 23874797, 2013).
pancreatic cancer (73 papers, 2010 to 2025). "Taken together, it seems that TH301 can activate the Caspase-3/PARP1 apoptotic axis in pancreatic cancer cell environments, following a mutational signature-dependent manner." (PMID 39796036, 2024). "In summary, our study elucidated the pivotal role of SMAD4, a gene commonly mutated in PDAC, in attenuating PARP1-mediated DNA repair and contributing to radiotherapy resistance in pancreatic cancer." (PMID 39528473, 2024). "Since SIRT6 cooperates with Poly [ADP-ribose] polymerase 1 (PARP-1) in the repair of DNA double-strand breaks, the effect of their inhibition was assessed in Capan 1 pancreatic cancer (PaC) cell lines with BRCA-2 deficiency." (PMID 38203666, 2023). "In other words, a series of biochemical phenomena associated with PARylation following PARP-1 activation can be a potential theory that can collectively explain the multifactorial process of pancreatic cancer progression." (PMID 33805293, 2021). "It was reported that PARP1 expression was negatively associated with breast, ovarian, and pancreatic cancer outcomes." (PMID 33262410, 2020). "Consequently, recent studies have confirmed that targeting PARP-1 has clinical benefits in BRCA-mutated patients with pancreatic cancer." (PMID 33805293, 2021). "Our results showed that ZQJ29 inhibits PARP1 activity, thereby triggering ferroptosis in pancreatic cancer cells, and exhibited significant anti‐pancreatic cancer activity both in vitro and in vivo." (PMID 40387570, 2025). "Ascorbate at millimolar levels significantly induces DNA damage through increasing high fluxes of H2O2 and activating Chk1 kinase and PARP1 pathways in pancreatic cancer cells." (PMID 39990670, 2025). "The PARP1‐targeted mechanism for inducing ferroptosis demonstrates promising capabilities to address critical clinical challenges in pancreatic cancer therapy." (PMID 40387570, 2025). "Recently, targeted therapies against PARP1 have been developed and approved for the treatment of BRCA-mutated breast, ovarian, and pancreatic cancers." (PMID 40303286, 2025). "In this study, ZQJ29, a novel artemisinin derivative with significant potential as an anti‐pancreatic cancer agent and a promising PARP1 inhibitor with a peroxide bridge structure, was synthesized." (PMID 40387570, 2025). "This study provides compelling evidence that ferroptosis can be induced through specific targeting of PARP1, offering new insights and innovative therapeutic strategies for addressing pancreatic cancer." (PMID 40387570, 2025). "This indicated that ZQJ29 induced ferroptosis in pancreatic cancer cells through a PARP1‐dependent pathway." (PMID 40387570, 2025). "Pancreatic cancer patients who received combined PARP1 and CD24 inhibition experienced a synergistic antitumor effect." (PMID 38279998, 2024). "ADP-ribosylation of the RNA helicase DDX5 by poly (ADP-ribose) polymerase 1 (PARP1) controls CD24 transcription in pancreatic cancer, according to research." (PMID 38279998, 2024). "Nuclear FBP1 has been found to interact with DNMT1 and to recruit PARP1 to chromatin, enhancing the sensitivity of pancreatic cancer to the poly ADP-ribose polymerase (PARP) inhibitor Olaparib." (PMID 39048965, 2024). "A recent study uncovered the cytoplasmic localization and function of PARP-1 in regulating DR5-activated extrinsic apoptosis pathways in pancreatic cancer cells." (PMID 38590714, 2024). "The success of novel target therapies with PARP1 inhibitors in pancreatic cancer has prompted further research into the role of DDR in pancreatic cancer development and progression." (PMID 39457488, 2024). "PARP1 binds to, and inhibits DDX5 by ADP-ribosylating DDX5 in pancreatic cancer cells (Fig. 3C1), which can be abolished by PARP1 inhibitor, talazoparib, while PARP1 inhibition increased DDX5 expression and binding to the CD24 promoter." (PMID 37596619, 2023). "The knockdown of PARP-1 dramatically boosted TRA-8-induced apoptosis in pancreatic cancer cells in vitro." (PMID 38006403, 2023).
pancreatic cancer (continued). "As expected, the gemcitabine and ABT-263 combination treatment promoted the death of the gemcitabine-treated and chemoresistant Capan2 pancreatic cancer cells according to blue trypan assay and PARP1 cleavage." (PMID 36739330, 2023). "In this study, we found that TSA and, even more effectively, VPA synergized with AZD2461, PARP1, 2 and 3 inhibitor (PARPi) to induce DNA damage and reduce pancreatic cancer cell survival." (PMID 35216385, 2022). "In the case of pancreatic cancer, previous studies have reported that the PARP-1 expression can be used as a marker of differential diagnosis between pancreatic cancer and other pancreatic disorders." (PMID 35453444, 2022). "PARP1 is upregulated in many types of human cancer including ovarian, breast and pancreatic cancers, and several PARP inhibitors have been developed for clinical applications." (PMID 36400783, 2022). "NUPR1 binds to PARP1 and inhibits PARP1 activity in pancreatic cancer cells, with the NUPR1 inhibitor ZZW-115 abolishing the protective effect of NUPR1, inducing strong hyperPARylation and cell death by mitochondrial dysfunction." (PMID 35869257, 2022). "Our study also revealed that PARP1 depletion attenuated the changes in PARP inhibitors sensitivity after knockdown or overexpression of FBP1 in pancreatic cancer cells." (PMID 34854226, 2022). "Together, these data indicated that FBP1 contributed to sensitivity to PARP1 inhibitors through the DNMT1‐PARP1 complex in pancreatic cancer." (PMID 34854226, 2022). "Veliparib, a PARP-1/2 inhibitor, was tested with gemcitabine and radiotherapy in locally advanced pancreatic cancer in a phase 1 study, and the results supported a phase 2 validation study." (PMID 35626021, 2022). "In other words, since the abnormal growth of pancreatic cancer constantly induces DNA damage, leading to genomic instability, the PARP-1 activity and PARylation play a major role in the adaptation to genomic instability in pancreatic cancer." (PMID 33805293, 2021). "Cytoplasmic PARP-1 is associated with sustained activation of Src-mediated survival signaling, whereas PARP-1 knockdown inhibits Src in pancreatic cancer cell lines." (PMID 33923319, 2021). "Another feature that is not directly involved in the DNA repair process of homologous recombination in pancreatic cancer is PARP-1 activation." (PMID 33805293, 2021). "PARP-1 plays critical roles in DNA damage repair during intrinsic cell death, and cytoplasmic PARP-1 was recently confirmed to promote pancreatic cancer tumorigenesis and resistance." (PMID 33731794, 2021). "The mechanistic roles of PARP-1 contributing to pancreatic cancer are being actively considered in various processes required for cancer cell survival, such as overcoming oxidative stress or genetic instability and regulation of mitosis and transcription." (PMID 33805293, 2021). "The most exploited target involved in DNA repair is the family of poly (ADP-ribose) polymerases or PARPs, particularly PARP-1/2 in pancreatic cancer." (PMID 33546207, 2021). "Nonetheless, these data clearly suggest that KP372-1 treatment induces PARP1 hyperactivation in NQO1-expressing pancreatic cancer cells." (PMID 33214574, 2020). "Profound DNA damage emanating from massive ROS production in pancreatic cancer cells strongly indicated potential hyperactivation of PARP1 after KP372-1 treatment." (PMID 33214574, 2020). "Similar to FGFR1, PARP1 mRNA expression (ILMN_1686871) was approximately 1.81-fold (p < 0.01) higher in dasatinib-resistant pancreatic cancer cells than in dasatinib-sensitive cells (lower)." (PMID 32276472, 2020). "Here, we show that KP372-1-induced robust DNA damage response ensuing hyperactivation of DNA damage sensor protein poly(ADP-ribose) polymerase 1 (PARP1) offers a promising targeted chemotherapeutic strategy against pancreatic cancer." (PMID 33214574, 2020). "KP372-1-induced PARP1 hyperactivation observed here is similar to that of β-lap treated pancreatic cancer cells." (PMID 33214574, 2020).
pancreatic cancer (continued). "Observed PARP1 hyperactivation in response to KP372-1 treatment suggested that pancreatic cancer cells rely on PARP1 activity to counteract cellular stress created by KP372-1." (PMID 33214574, 2020). "In this work we have examined the role of PARP-1 in the activation of the transcription of KRAS in pancreatic cancer cells." (PMID 32872305, 2020). "Accordingly, ectopic BMI1 also abrogated significantly the induction of apoptosis promoted by SOX9 silencing, reducing by over 50% the percentage of cells with active Caspase-3 and proteolyzed PARP1 in gastric and pancreatic cancer cells." (PMID 31941916, 2020). "Veliparib is an oral PARP-1/2 inhibitor and has been tried as monotherapy or in combination with a platinum-containing regimen in patients with pancreatic cancer." (PMID 31382681, 2019). "In pancreatic cancer, autoantibody frequency to three TAAs (PARP1, BRCA1 and BRCA2) were 0% (0/41), 7.3% (3/41) and 0% (0/41)." (PMID 25865228, 2015). "In order to compare the induction of cell death on colon and pancreatic tumor cells by the different RE's we analyzed PARP1 cleavage by western blot." (PMID 24892299, 2014). "The work first demonstrates that targeting PARP1 can induce ferroptosis in pancreatic cancer." (PMID 40387570, 2025). "Additionally, these investigations have unveiled ZQJ29 as a new potent PARP1 inhibitor, with the capability to induce ferroptosis in pancreatic cancer cells." (PMID 40387570, 2025). "Hence, we examined total protein levels and cleavage patterns of the fundamental apoptosis mediators PARP1 and Caspase-3, after treatment of the three pancreatic cancer cell lines with the TH301 circadian clock modulator, for 24 and 48 h." (PMID 39796036, 2024). "However, only 5-10% of pancreatic cancer patients have germline or somatic mutations in the BRCA1 or BRCA2 genes, which limits the application of therapies involving PARP1." (PMID 39528473, 2024). "PARP‐1 cytoplasmic mutant promoted the tumorigenesis and resistance of pancreatic cancer." (PMID 37491836, 2023). "As a potent inhibitor of PARP1, olaparib and its combination with agents targeting apoptosis signaling could represent an effective therapeutic option in pancreatic cancer." (PMID 36358659, 2022). "Deficiency in PARP1 has also been shown to accelerate both aging and spontaneous tumorigenesis in mice, while high PARP expression has been associated with improved survival in pancreatic cancer patients." (PMID 35666002, 2022). "This understanding could help to embrace the importance of targeting PARP-1 in the treatment of pancreatic cancer, which may present the potential to find out a variety of research topics that can be both challenged clinically and non-clinically." (PMID 33805293, 2021). "This review summarizes the current molecular biological knowledge to understand the multifactorial functions of PARP-1 that enable the progression of pancreatic cancer, and the approaches and outcomes of PARP-1 inhibition in clinical studies targeting pancreatic cancer are also discussed." (PMID 33805293, 2021). "A novel 14-gene signature comprising CCDC148, SH3RF2, CACNA1D, POLD3, PARP1, AP1M2, C4orf19, ANO1, VGLL1, SCEL, INPP4B, NET1, INSIG2 and BVES and a corresponding risk score formula were established for pancreatic cancer risk stratification and prognosis prediction." (PMID 33731794, 2021). "Therefore, it can be stated that PARP-1 can also be considered as an important marker for identifying the critical relationship between transcription regulation and the development of pancreatic cancer." (PMID 33805293, 2021). "In 2005, two efforts highlighted the synthetic lethal interaction between PARP1 inhibition and loss of BRCA1 or BRCA2, which lead to the development of approved clinical PARP inhibitors in ovarian, breast or pancreatic cancer treatments in case of BRCA1 or BRCA2 loss-of-function." (PMID 34439361, 2021).